AKT2 (AKT serine/threonine kinase 2)
Diseases named in the same sentence as AKT2 in open-access papers (continued):
Sharing a sentence is not in itself a finding about the gene and the disease.
glioma (35 papers, 2012 to 2026). A benign or malignant brain and spinal cord tumor that arises from glial cells (astrocytes, oligodendrocytes, ependymal cells). "TWEAK-Akt association has been shown in other systems, such as the heart, skeletal muscles, and tumors, including glioma, where Akt2 was specifically implicated in mediating TWEAK-induced cell survival." (PMID 34440346, 2021). "Glioma-associated DEGs AKT2, CCL3, STAT2, VEGFC were up-regulated and HIF1A, KRAS, RET, TGFB2 were down-regulated specifically in the dogs." (PMID 29352201, 2018). "Mutations in AKT1 have been associated with schizophrenia, AKT2 with gliomas and AKT3 with brain growth." (PMID 29173281, 2017). "AKT2 also has been associated with glioma, a type of brain cancer with malignant tumors derived from glial cells." (PMID 29173281, 2017). "We queried the cancer genome atlas database and utilised bioinformatic analysis to report that AKT2 mRNA was highest in low-grade glioma, and also the high expression correlates with poor patient survival." (PMID 36120909, 2022). "Our results confirm reported investigations and show that AKT1 and AKT2 act as promoters of glioma tumorigenesis, while AKT3 shows a tumor-suppressor role." (PMID 34209611, 2021). "Mechanistically, it was demonstrated that AEG-1 interacts with Akt2, resulting in the prolonged stabilization of Akt S474 phosphorylation and activation of downstream signaling in glioma cells." (PMID 33918653, 2021). "In TCGA database among 372 patients with glioma, who were separated into high- or low-Akt2 expressing groups, high-expressing Akt2 patients demonstrated poorer OS (p < 0.0001)." (PMID 33671513, 2021). "AKT2 plays a role in the migration and invasion of glioma cells and expression correlates with the malignancy of gliomas." (PMID 33053751, 2020). "Among the selected genes, 15 (Araf, Braf, Kras, Ccnd1, Cdk6, Igf1r, Nras, Pik3ca, Pik3r1, Pdgfra, Pdgfrb, Pdgfb, Akt1, Akt2, and Mdm2) were related to glioma and leukemia." (PMID 31523185, 2019). "In glioma, expression of Akt3 mRNA and protein decreases as the malignancy grade increases, in parallel with increased Akt2 mRNA and protein." (PMID 29518912, 2018). "Akt1 is the most well characterized isoform of the three, but in recent years, it has become evident that Akt2 and Akt3 are more important than is Akt1 in glioma development and progression." (PMID 26993778, 2016). "For example, chemotherapeutic resistance in glioma cells has been shown to be promoted through Rac1-dependent Akt2 activity working upstream of the BCL2 family to promote cell survival." (PMID 24109588, 2013). "Elevated levels of p-Akt/PKB have been shown to positively correlate with migrating glioma cells, and reduction of total Akt2/PKBβ has been shown to inhibit the migratory as well as the invasive potential of glioma cells." (PMID 23451269, 2013). "A recent report shows that a significant reduction of AKT2 levels and phosphorylation of Akt was detected after knockdown of Tcf-4 using Tcf-4 siRNA in glioma cells." (PMID 23029137, 2012). "In glioma cell lines, AKT2 or AKT3 knockdown inhibited cell growth and induced apoptosis." (PMID 38911393, 2024). "However, it is important to note that the MK-2206 biochemical IC50 for AKT2 is 12 nM, which is 1000-fold higher than 12 μM of 4j, MK-2206 was expected to exhibit very high potency in glioma where AKT expression and signalling pathway are amplified." (PMID 36120909, 2022). "Aberrant AKT2 signalling is common in many cancers, such as glioma." (PMID 36120909, 2022). "Other loci were found altered such as Aldehyde dehydrogenase 2 (ALDH2) and isocitrate dehydrogenase 2 (IDH2), that was found to predispose to cervical carcinoma and glioma respectively as well as BCL3, AKT2 and ERCC2 for which polymorphisms were shown to be associated with lung carninoma." (PMID 31105870, 2019).
glioma (continued). "Interestingly, in a recent study, the Akt1 isoform was unable to induce PDGF-dependent high-grade glioma in a genetically engineered tumor model, whereas Akt2 and Akt3 isoforms strongly promoted high-grade glioma progression." (PMID 29562639, 2018). "Likewise, AKT1 and AKT2 found to be related to bcatenin/Tcf-4 signaling pathway that promoted malignant transformation in human LN229 glioma cell line." (PMID 29890617, 2018). "AKT2 was found to be especially necessary for glioma cell migration." (PMID 29890617, 2018). "More interestingly, these Akt2-deficient gliomas were not able to generate brain tumours upon implantation in immunodeficient mice, unlike glioma-derived controls." (PMID 29518912, 2018). "Thus, AKT1 and AKT2 were considered as valuable targets for glioblastoma therapy as well as a rational strategy for restraining the metastasis of gliomas." (PMID 29890617, 2018). "Whether miR-184 inhibits glioma survival by blocking the PI3K/AKT2 pathway needs further investigation." (PMID 25888093, 2015). "Indeed, AKT2 levels correlated with glioma malignancy and poorer patient survival." (PMID 36120909, 2022). "Additionally, LINC00152 regulates PMT in glioma via the miR-612/AKT2/NF-kB axis." (PMID 33028341, 2020). "Therefore, we conclude that increased ERBB3 abundance and PIK3R1 expression and decreased ERBB2, FGFR3, and AKT2 expression may explain the improved LGG patient survival in IDH-mutant gliomas compared with IDH-wildtype gliomas." (PMID 27852048, 2017). "AKT2 has been shown to modulate chemoresistance by downregulating MDR1 and MRP1 in various malignancies, including ovarian, endometrial, breast, gliomas, and renal carcinomas." (PMID 41303548, 2025). "AKT is an established oncogenic kinase with at least three mammalian isoforms AKT1/PKBα, AKT2/PKBβ, and AKT3/PKBγ of which AKT2 plays major pro-oncogenic roles in cancers, including glioma." (PMID 36120909, 2022). "Data on CNA show that genes AKT2, AKT3, CHUK, EGFR, PIK3AP1, and PTEN show an increase in copy number alterations with the increased glioma grade." (PMID 34209611, 2021). "In primary human glioma tumor samples, AEG-1 and Akt2 were found to be upregulated when compared with normal brain tissues by IHC analysis." (PMID 33671513, 2021). "The Kruskal–Wallis test confirmed a significant difference in methylation of all examined genes between glioma types (p < 0.001 for AKT1, AKT3, CHUK, GSK3β, EGFR, PTEN, PIK3AP1; p = 0.032 for AKT2)." (PMID 34209611, 2021). "AEG-1 interacts with Akt2 to prolong Akt activation, which is required for the growth and survival of glioma, and the inhibition of the AEG-1-Akt interaction rendered glioma cells as more sensitive to temozolomide (TMZ)." (PMID 33918653, 2021). "AKT2, pAkt, pNF-κB, and MDR1 were significantly up-regulated in the glioma model than in normal tissue and were attenuated through celecoxib treatment." (PMID 34301977, 2021). "Other alterations we observed that would be expected to cooperate with PI3K activation included AKT2 and PDGFRA over-expression, both also frequent aberrations observed in glioma." (PMID 33053751, 2020). "We randomly selected four additional genes (AKT2, AKT3 GRB2 and MMP2) from the “glioma” pathway, other than the validated targets of the key miRNAs.to check for downstream effect of miRNA overexpression." (PMID 29769662, 2018). "Activation of Akt2 led to increased MMP-9 expression and increased glioma cell migration and invasion." (PMID 24109588, 2013). "Compound 4j inhibited AKT2/PKBβ specifically among 139 purified kinases tested and induced cell death in primary patient-derived glioma 2D cells and 3D neurospheres while being relatively nontoxic towards non-cancerous cells." (PMID 36120909, 2022). "Lower grade gliomas, the AA group, harbored the highest number of CNA in genes PTEN (50%), PIK3AP1 (49%), and CHUK (49%), while the DA group carried the highest number of CNA in genes AKT1 (15%), AKT2 (11%), and GSK3β (11%)." (PMID 34209611, 2021).
glioma (continued). "AKT pathway genes AKT2 and AKT3, which contribute to glioma invasiveness and malignancy, and class II myosins, required for glioma invasion and neural stem cell migration, were also progressively up‐regulated as one moves along the backbone of the SF10345 phylogeny." (PMID 27888226, 2016). "With respect to brain tumors, the level of AKT1 found in glioma cells and tissues was more similar to that found in normal human astrocytes or non-neoplastic regions of the brain; whereas AKT2 levels were increased, and AKT3 levels were decreased." (PMID 22480225, 2012). "Based on the TCGA data, we confirmed that AKT2, but not AKT1 or AKT3, interacts with PDCD4, thus leading to the suppression of PDCD4 in glioma cells." (PMID 33304903, 2020). "Taken together, these data suggest that AKT2, but not AKT1 or AKT3, interacts with and suppresses PDCD4 in the glioma cells." (PMID 33304903, 2020). "Here, we present evidence that AKT2, but not AKT1 or AKT3, interacts with PDCD4 leading to its suppression in glioma cells, and is consistent with the inverse relationship between mRNA levels of AKT2 and PDCD4 observed in the TCGA data analysis." (PMID 33304903, 2020).
lung carcinoma (35 papers, 2012 to 2025). "To this aim we suppressed AKT1 and AKT2 expression in an established lung cancer cell line (NCI-H460) that harbours an activating mutation of PIK3CA (E545K) as reported." (PMID 27880728, 2017). "Patients with the TT genotype of PI3CA: rs9838117, the AA genotype of AKT2: rs33933140, and the CT+TT genotype of AKT2: rs11880261 had a significantly increased risk of RP after radiotherapy for lung cancer." (PMID 26645682, 2016). "Using our transgenic mouse model of IGF-IR driven lung cancer, we found that loss of Akt1 suppressed while loss of Akt2 augmented, lung tumor development." (PMID 26654940, 2016). "We report that Akt1 ablation inhibits the incidence and development of lung tumors, Akt2 deficiency markedly accelerates lung tumor initiation and Akt3 ablation slightly enhances tumor progression in this mouse model of lung cancer." (PMID 24722238, 2014). "Higher AKT2 expression levels are associated with lung cancer, and osteosarcoma." (PMID 38577021, 2024). "High AKT2 mRNA expression was also substantially associated with a poor OS in patients with lung cancer (HR, 1.67; 95% CI, 1.41–1.97; P=1.2e−09) and patients with LUAD (HR, 2.35; 95% CI, 1.82–3.02; P=9.7e−12), but not in patients with SqCLC (HR, 1.35; 95% CI, 0.98–1.86; P=0.062)." (PMID 36945793, 2022). "To verify this hypothesis, we selected seven potentially functional SNPs from three genes in PI3K/AKT signaling pathway, PI3CA, AKT1, and AKT2 to discover their potential associations with the occurrence of severe RP in lung cancer patients treated with radiation therapy." (PMID 26645682, 2016). "Akt1 and Akt2 were characterized as suppressors for E-cadherin expression in PANC-1 as well as H23 lung carcinoma cells." (PMID 38291468, 2024). "Western blot analyses revealed pronounced reduction of E-cadherin and NCAM in the Akt3-kd cells, whereas Akt1 and Akt2 depletion upregulated E-cadherin, especially in H23 lung carcinoma cells." (PMID 38291468, 2024). "High expression of AKT1, AKT2 and AKT3 was significantly associated with a OS in patients with clinical stage I lung cancer, and high expression of AKT3 was also found to be associated with a reduced OS in patients with clinical stage II lung cancer." (PMID 36945793, 2022). "MiR-497 highlighted its role and sensitized lung cancer cells to CDDP treatment in an AKT2-dependent manner." (PMID 33015042, 2020). "Cell viability rate of 5 μM CDDP treatment were measured by CCK-8 assay at different time points, which showed that overexpression of AKT2 rendered cancer cells more chemoresistance in miR-497-overexpressing lung cancer cells." (PMID 33015042, 2020). "In summary, this study suggested that miR-497/AKT2 regulatory axis in lung cancer, which miR-497 negatively regulates AKT2 oncogene expression and functions as a tumor suppressor." (PMID 33015042, 2020). "This study will questions to classify the roles and mechanisms of miR-497 in lung cancer tumorigenesis, be useful for developing new miR-497/AKT2 -based prognostic marker or/and treatment option." (PMID 33015042, 2020). "This study firstly provides the evidence that miR-497 is important in abating lung cancer tumorigenesis through inhibiting AKT2 translation." (PMID 33015042, 2020). "This study investigated the role of miRNAs as effectors of increasing the AKT1 and AKT2 gene numbers within lung carcinomas." (PMID 30845775, 2019). "Here, we not only demonstrate the suppression of AKT2 is the route by which miR-29c functions as a tumor suppressor gene but also confirmed it is the route by which miR-29c regulates lung cancer cell cisplatin resistance genesis." (PMID 29789623, 2018). "Attoub S. and colleagues reported that AKT2 played an important role in lung cancer cell proliferation, motility, invasion and angiogenesis." (PMID 28404925, 2017).
lung carcinoma (continued). "Akt1 or Akt2 knockout in a viral oncogene-induced mouse model of lung cancer demonstrated that Akt1-ablation inhibited, whereas Akt2-ablation enhanced lung tumour initiation, highlighting their functionally diverse roles." (PMID 28082369, 2017). "Current study evaluated the genetic variants of PIK3CA, AKT1, and AKT2, all of which are genes in PI3K/AKT pathway, to discover their potential associations with the occurrence of RP in lung cancer patients with radiotherapy." (PMID 26645682, 2016). "On the contrary, a very recent study using a viral oncogene-induced mouse model of lung cancer, showed a dramatic increase in tumorigenesis in Akt2-/- mice due to the enhancement of cell proliferation and inhibition of apoptosis." (PMID 26234648, 2015). "We demonstrate that Akt2 is a key signaling kinase for lung cancer cell motility, invasion, and for angiogenesis in vitro." (PMID 26234648, 2015). "Altogether, these results indicate that Akt2 plays an important role in lung cancer progression and can be a promising target for lung cancer therapy." (PMID 26234648, 2015). "Altogether, these results strongly suggest that both Akt1 and Akt2 plays a role in lung cancer cell invasion and perhaps - by extrapolation - in metastasis." (PMID 26234648, 2015). "We decided to use the highly tumorigenic and metastatic lung cancer cells LNM35 to investigate the impact of specific silencing of the Akt1 and Akt2 isoforms on human lung cancer progression." (PMID 26234648, 2015). "Discordant data have been reported about the role of Akt2 in cancer cell migration and invasion, but majority are in agreement with our current data indicating that Akt2 is required for the invasive potential of lung cancer cells." (PMID 26234648, 2015). "In this study, we demonstrate that the Akt2 isoform plays an important role in lung cancer cell proliferation, colony, and tumor growth, as well as in motility, invasion, and angiogenesis." (PMID 26234648, 2015). "Our data demonstrate that Akt2 is necessary for lung cancer cell proliferation, colony and tumor growth in accordance with the decrease in Rb phosphorylation." (PMID 26234648, 2015). "Besides, highly phosphorylated PDGFRA has been observed in non‒small cell lung cancer and rhabdomyosarcoma, AKT2 and AKT3 are the serine/threonine kinases that regulate cellular metabolism, cell proliferation, cell survival, cell growth and angiogenesis." (PMID 35399006, 2022). "Taken together, we showed that miR-497/AKT2 may be potential new lung cancer biomarkers, which would be interesting for further investigation." (PMID 33015042, 2020). "In addition, an immunohistochemistry assay similarly showed higher AKT2 protein levels in lung cancer tissues than in normal tissues." (PMID 32873299, 2020). "In addition, we demonstrate that miR-497 sensitizes lung cancer cells to CDDP treatment in an AKT2-dependent manner." (PMID 33015042, 2020). "However, in lung cancer, a partial reduction in scratch wound healing migration was observed in Akt2 knockdown cells while the prominent effect was observed in Akt1 knockdown cells." (PMID 31252679, 2019). "In consequence, AKT2 showed obviously declining upon miR-29c overexpression comparing to negative control mimic transfection in both mRNA level and protein level in the two cell lines, indicating AKT2 is also a direct target of miR-29c in lung cancer." (PMID 29789623, 2018). "To test whether it can also target AKT2 in lung cancer, we first performed dual luciferase reporter assay and demonstrated that miR-29c could bind AKT2." (PMID 29789623, 2018). "We first used the expression profiling data to determine the human lung cancer subtype we were modeling in the SPC-IGFIR and SPC-IGFIR-Akt2−/− tumors and whether loss of Akt2 altered the lung tumor subtype." (PMID 26654940, 2016).
lung carcinoma (continued). "RNA sequencing revealed a number of genes differentially expressed in lung tumors lacking Akt2 and five of these genes, Actc1, Bpifa1, Mmp2, Ntrk2, and Scgb3a2 have been implicated in human lung cancer." (PMID 26654940, 2016). "We investigated the impact of specific silencing of Akt1 and Akt2 on human lung cancer cell proliferation, colony growth, motility, and invasion in vitro as well as tumor growth in vivo using human Non-Small Cell Lung Cancer cells LNM35, and on the vascular tube formation using HUVEC cells." (PMID 26234648, 2015). "Akt2 ablation on the other hand, dramatically accelerates lung tumor initiation via enhanced proliferation and suppression of apoptosis suggesting that Akt2 activity may have a protective effect in lung cancer." (PMID 24722238, 2014). "Furthermore, it has been previously demonstrated that the enforced expression of miR-29c enhances cisplatin sensitivity in lung cancer cells by targeting AKT2, while the silencing of miR-29c promotes cisplatin resistance in cancer cells by activating the PI3K/Akt pathway." (PMID 40805201, 2025). "Network pharmacological analysis identified PIK3CG, SRC, JAK3, AKT2, and PRKCA as key potential targets of peiminine in lung cancer treatment." (PMID 40331978, 2025). "Survival analysis indicated that a high AKT2 and PRKCA expression correlated with bad prognosis in lung cancer patients." (PMID 40331978, 2025). "Analysing public data sets revealed that gene expression of the PI3K‐MAPK downstream effectors, AKT2 and BRAF, positively correlated with USP28 in lung cancer cell lines and in various tumour entities." (PMID 35364627, 2022). "The data demonstrated, that only SNAI2 mRNA was affected, although differentially in the two cell lines, with a downregulation in the H23 lung carcinoma and upregulation in PANC-1 K-Ras(V12)/Akt2-kd clone A contribution of Akt in Slug/SNAI2 regulation is not without presence in the literature." (PMID 38291468, 2024). "Additionally, the identified targets (PIK3CG, SRC, JAK3, AKT2, and PRKCA) may function as possible biomarkers for predicting lung cancer prognosis and guiding personalized therapy." (PMID 40331978, 2025). "Additionally, AKT3, but not AKT2 depletion, was found to inhibit proliferation and survival of lung cancer derived disseminated human tumor cells." (PMID 24946858, 2014). "The potential opposing roles of Akt1 and Akt2 in lung tumorigenesis suggest that development of non-selective Akt inhibitors may not be beneficial and in fact, may be detrimental, particularly in the case of lung cancer in never smokers." (PMID 24722238, 2014).